INS (insulin)
Diseases named in the same sentence as INS in open-access papers (continued):
Sharing a sentence is not in itself a finding about the gene and the disease.
cancer (continued). "Metformin and thiazolidinediones (TZDs) are commonly prescribed to restore insulin sensitivity in type II diabetes, and patients taking either medication often experience improved response to chemotherapy and lower cancer incidence in randomized trials." (PMID 28959684, 2017). "Focal adhesion, ECM-receptor interaction, and insulin pathway in other modules were also discovered in previous cancer DEGs studies." (PMID 28212608, 2017). "Upregulation of insulin-independent glucose transporters such as glucotransporter-1 (Glut-1) favors glucose uptake by cancer cells." (PMID 28060743, 2017). "In the leptin/adiponectin relationship, this measurement can be considered to be an indicator of sensitivity to insulin in youth who have survived childhood cancer." (PMID 28193268, 2017). "If started late in life, the experiments will take just several months to evaluate the effect on lifespan and cancer incidence as well as weight, blood pressure, glucose, insulin, triglycerides and leptin." (PMID 28548953, 2017). "It is thought to exert its anti-cancer effect via two mechanisms—directly by acting on the tumour and indirectly by lowering systemic insulin levels." (PMID 28444639, 2017). "Simultaneously, metformin induced lower insulin concentrations are anti-proliferative to insulin sensitive cancers." (PMID 28698465, 2017). "In conclusion, our study demonstrates the pioneer use of novel thioglycosides with supplementary insulin to selectively target cancer cells in vitro." (PMID 29371977, 2017). "RSV is able to block glucose uptake in cancer cells, affecting the survival, while in skeletal muscle and adipose tissue, it enhances insulin-stimulated glucose uptake." (PMID 28272357, 2017). "Due to its complex influence on malignant cell metabolism, insulin has been exploited as a potential sensitizing agent in cancer therapy." (PMID 29371977, 2017). "IGF-1, a well-known pathway with an affinity for insulin, is also critical to cell proliferation and apoptosis and has been shown to be related to various types of cancers." (PMID 29228629, 2017). "It is known that adiponectin not only possesses anti-atherosclerotic, anti-inflammatory, and insulin-sensitizing properties, but it also has protective effect against cancer." (PMID 29088874, 2017). "Taken together, this study provides an insight of insulin sensitizers-mediated cancer metabolism into understanding the prognostic benefit as well as therapeutic potential of the PPARγ in the cancer clinic." (PMID 29137280, 2017). "In tumour progression, several studies have demonstrated the impact of the insulin/IGF system on cancer cell behaviour, particularly on the acquisition of the malignant phenotype by regulating the epithelial-mesenchymal transition (EMT) program." (PMID 28880250, 2017). "The indirect mechanism of metformin in anti-cancer function is related to its ability to lower insulin and insulin-like growth factor 1 (IGF-1)." (PMID 27902459, 2017). "Calorie restriction and associated dietary restriction seem to exert their effects specifically through mTOR, AMPK, and glucose handling (IGF/insulin) pathways with outcomes such as lifespan extension, reduced inflammation and cancer." (PMID 28966808, 2017). "Epidemiological evidences indicate that insulin secretion rate and insulin-like growth factor-1 (IGF-1) level influence cancer risk and/or cancer prognosis." (PMID 28978182, 2017). "Despite this evidence, the impact of O-GlcNAc in the modulation of the insulin/IGF system in cancer remains poorly understood." (PMID 28880250, 2017). "Changes in the insulin/IGF system can also be involved in the acquisition of the aggressive cancer phenotype." (PMID 28880250, 2017). "In the present study, we found that 22–63% of cancer cases were diagnosed within the first year after starting insulin treatment." (PMID 28573394, 2017).
cancer (continued). "By activating those signalling pathways, insulin/IGF coordinates multiple processes frequently deregulated in cancer, including cellular growth, proliferation, metabolism, and cell survival." (PMID 29615570, 2017). "Specifically, the IR-A, which is predominantly expressed by fetal and cancer cells, exerts proliferative and protumoral effects in response to insulin, proinsulin, and IGF-II." (PMID 28275367, 2017). "In this study among postmenopausal women, we examined the pathway of glucose metabolism genetic variants, glucose metabolism traits (fasting insulin, glucose, and HOMA-IR levels), and cancer risk." (PMID 28446149, 2017). "Although the primary role of these TFs is to restore ER homeostasis, new lines of evidence suggest that they provide functions in other physiological or pathological processes, including immune responses, cancer development, and insulin signaling." (PMID 28860159, 2017). "Several mechanisms can lead to an imbalance of the insulin/IGF signaling network in cancer, including the increased bioavailability of the ligands, dysregulation of signaling proteins, and overexpression of the receptors." (PMID 28880250, 2017). "Although these results support the importance of glycans interplaying with the insulin/IGF system in cancer, further studies are required on this topic." (PMID 28880250, 2017). "CaMKK2 controls insulin signaling, metabolic homeostasis, inflammation and cancer cell growth highlighting its potential as a therapeutic target for a variety of diseases." (PMID 28924233, 2017). "Saos-2/B10 cells have been used to assess cancer-related safety of insulin analogues (IR binding agonists) with a focus on mitogenic potency, receptor activation and binding studies." (PMID 28316059, 2017). "Insulin and insulin-like growth factor signaling pathways were suggested as one of mechanisms linking height to cancer." (PMID 28636624, 2017). "It is widely known that cancer cells express insulin as well as Insulin-like Growth Factor (IGF), Insulin-like Growth Factor Receptors (IGF-R) and that, besides its metabolic effect, IGF-R promotes proliferation and metastasis." (PMID 28373897, 2017). "The results showed that the TCR, BCR, MAPK, insulin, and Wnt pathways as well as various cancer signaling pathways were targeted by miR-155." (PMID 27532002, 2016). "There is some evidence that insulin-treated patients have a higher cancer incidence compared with non-insulin-treated patients." (PMID 26924393, 2016). "The insulin/IGF network is tightly connected to cancer development, because it mediates cell growth, proliferation, differentiation and participates in metabolic activities." (PMID 27849005, 2016). "In fact, ATGL abundance is regulated by multiple players including members of the insulin signaling network, which are reported to be frequently altered in cancer cells." (PMID 27213586, 2016). "The adjusted hazard ratios (aHRs) for people prescribed insulin plus metformin versus insulin monotherapy were 0.60 (95% CI 0.52–0.68) for all-cause mortality, 0.75 (0.62–0.91) for MACE, and 0.96 (0.80–1.15) for cancer." (PMID 27152598, 2016). "The choice of insulin appeared to have an even greater impact on cancer related mortality than on cardiovascular mortality." (PMID 27031113, 2016). "A large body of preclinical data has indicated that inhibition of the insulin/IGF-1 system has a therapeutic benefit for cancer-bearing animals." (PMID 26878387, 2016). "(ii) Insulin-lowering drugs such as metformin and diazoxide provide another opportunity for improving cancer outcome in patients." (PMID 26878387, 2016).
cancer (continued). "TRIB3 depletion not only protects against the tumor‐promoting actions of insulin/IGF in cancer cells, but also suppresses tumor initiation, growth and metastasis in diabetic mice." (PMID 27038142, 2016). "Diabetics treated with metformin have 25–40% reduced incidence of cancer compared to those who receive insulin as therapy or take sulfonylurea drugs that increase insulin secretion from the pancreas." (PMID 28018856, 2016). "More patients receiving insulin monotherapy had a history of large vessel disease (27% vs 14% for insulin monotherapy and insulin plus metformin, respectively, p<0.001) and cancer (12% vs 8%, p<0.001)." (PMID 27152598, 2016). "The aberrant glucose metabolism is one of the hallmarks of cancer cells, and as a branch of glucose metabolism, hexosamine biosynthesis pathway (HBP) has been reported to play a critical role in the insulin resistance and progression of cancer." (PMID 27996048, 2016). "When insulin was combined, the anticancer effects of 2DG were enhanced and the cancer promoting effects of insulin were reversed." (PMID 26939025, 2016). "Although somewhat counterintuitive, reports have been published suggesting that insulin can be used therapeutically to treat cancer under certain conditions." (PMID 26878387, 2016). "For cancer (after excluding people with a history of cancer), 158 and 121 events were observed for people treated with insulin monotherapy and insulin plus metformin, respectively." (PMID 27152598, 2016). "The decisive components in these metabolic pathways, including insulin, insulin-like growth factor (IGF), IGF-binding protein and insulin resistance, are also involved in regulating cancer cell proliferation and apoptosis." (PMID 27245112, 2016). "The results showed that 2DG had inhibitory effects on cancer cell while insulin had direct promoting effects." (PMID 26939025, 2016). "In contrast to other antidiabetic drugs (including sulfonylurea, insulin, thiazolidinediones and incretin-based therapies) that may show an increased risk of cancer, metformin was first noted to be associated with a reduced risk of cancer in an observational study in 2005." (PMID 27587088, 2016). "Similar challenges can be overcome through the use of messaging in immunization campaigns, insulin therapy, and cancer management." (PMID 27287668, 2016). "Insulin/insulin-growth factor-1 (IGF-1) axis markers and abnormal levels of adipokines have been implicated as underlying, in part, the obesity-cancer relationship." (PMID 27930694, 2016). "Across all insulin users, the aHR for cancer in relation to an increase in cumulative mean insulin dose of 1 unit/kg/day was 1.26 (95% CI 1.02–1.55)." (PMID 27152598, 2016). "PPARs as a super family are known to be involved in various physiological pathways including reproductive hormone synthesis, fatty acid metabolism, insulin function, immunology, central nervous system functions, and cancer development." (PMID 27983712, 2016). "ACC is an endocrine tumor where the massive secretion of IGF2 acts in an auto/paracrine loop to sustain cancer cell proliferation, via activation of both insulin and IGF-1R pro-survival intracellular pathways." (PMID 27391065, 2016). "Adiponectin is considered to play a protective role in cancer progression involving anti-inflammation, sensitization of insulin signaling and anti-angiogenesis." (PMID 27703473, 2016). "We have demonstrated that alternative splicing of the IR can be manipulated by different exposures and that the relative levels of these isoforms will influence how the cancer cells respond to both insulin and IGF-II." (PMID 27733843, 2016). "The results of cellular proliferation and apoptosis assays suggested that insulin promoted the anticancer effects of 2DG and that 2DG reversed the cancer promoting effects of insulin." (PMID 26939025, 2016). "Several metabolic risk factors, including insulin and IGF‐1‐enhanced TRIB3 expression in a diversity of human cancer cells." (PMID 27038142, 2016).
cancer (continued). "Previous study showed that Ras-Raf-MAPK signal, which acts as downstream of insulin/IGF-1 signaling plays a role in the proliferation of various cancers." (PMID 26901856, 2016). "Target pathways predicted for these miRNAs included ones involved in cancer, metabolic regulation, insulin signaling, and inflammation." (PMID 26733244, 2016). "Anti-cancer agent doxorubicin (DOX) has been demonstrated to worsen insulin signaling, engender muscle atrophy, trigger pro-inflammation, and induce a shift to anaerobic glycolytic metabolism in skeletal muscle." (PMID 27512375, 2016). "This indicates a broad spectrum of possibilities for modulating the insulin/IGF-1 system in cancer treatment." (PMID 26878387, 2016). "Activation of the insulin pathway can lead to cancer progression and resistance to current treatment modalities, including RT." (PMID 26977321, 2016). "Since insulin can stimulate the cellular uptake of hexose, including 2DG, the combination of 2DG and insulin improved the cytotoxicity of 2DG and meanwhile overcame the cancer-promoting effects of insulin." (PMID 26939025, 2016). "It has been widely accepted that insulin or IGF-1 promotes the proliferation of various cancers by activating MAPK signalings." (PMID 26901856, 2016). "Epidemiologic data linking metabolic markers-such as insulin, insulin-like growth factors (IGFs)-and adipose tissue-derived factors with cancer are inconsistent." (PMID 27930694, 2016). "One approach is to utilize the glucose-lowering effects of insulin to withdraw this preferred metabolic substrate from cancer cells." (PMID 26878387, 2016). "Insulin is involved in the biological mechanism, and it can accelerate cell division and consequently promote cancer progression." (PMID 27333326, 2016). "Looking forward, the incorporation of immunohistochemical staining for ketolytic/glycolytic enzymes and biomarkers (i.e. leptin, insulin) and their role in tailoring metabolic cancer management merits further study." (PMID 27525031, 2016). "In carcinogenesis, growth factors, such as IGF1 and insulin, stimulate growth and progression of cancer." (PMID 27255182, 2016). "Fourth, the high levels of insulin and insulin-like growth factors and chronic inflammatory status of cancer patients with hyperglycemia can inhibit apoptosis and promote metastasis." (PMID 27851819, 2016). "The insulin/insulin-like growth factor-1 (IGF-1) system has thereby emerged as a key regulator of cancer growth pathways." (PMID 26878387, 2016). "A growing body of evidence shows that the insulin signaling system has a key role in cancer development and progression." (PMID 27942580, 2016). "One the one hand, insulin promoted 2DG uptake by cancer cells and increased the anticancer efficiency of 2DG." (PMID 26939025, 2016). "The potential targets of these miRNAs included 136 cancer, 69 axon guidance and 67 insulin signaling pathway genes." (PMID 26799631, 2016). "MiR-103 has a key role in regulating insulin sensitivity in adipocytes by targeting caveolin-1, and in cancer cell growth and metastasis by repressing different targets, including KLF4 (refs 48, 58, 59)." (PMID 26837267, 2016). "It was identified that high levels of insulin and IGFs can promote cancer development through insulin/IGF axis, and especially that IGF-1 plays an important role in the inhibition of apoptosis and promotion of cell-cycle progression." (PMID 27509022, 2016). "The significantly divergent pathways of differentially expressed genes mainly include pathways in cancer (234; 4.6 %), focal adhesion (220; 4.3 %), regulation of actin cytoskeleton (212; 4.2 %) and insulin signaling pathway (154; 3 %)." (PMID 26968659, 2016). "This is thought interesting since metformin exerts its anti-cancer effects even in lean rodents which appear to have normal state of insulin and adipokine secretions." (PMID 25879666, 2015).
cancer (continued). "Our finding suggests that in addition to lower circulating insulin and direct inhibitory effects on cancer cells, the TAMs by is a potential new in the understanding the benefit in cancer therapy." (PMID 26497364, 2015). "Our study establishes the stress protein TRB3 as a molecular link connecting insulin/IGF to cancer promotions." (PMID 26268733, 2015). "In contrast, diabetic treatments, such as sulfonylureas, have been shown to increase mortality in patients with cancer and type 2 diabetes and insulin replacement has been shown to increase mortality due to its mitogenic effects." (PMID 25866793, 2015). "By contrast, we were surprised to find that rapid-acting, long-acting, and combination insulin treatment had a tendency to reduce the development of cancer at any site." (PMID 25978841, 2015). "TRB3 depletion protects against the tumour-promoting actions of insulin/IGF in cancer cells and suppresses tumour initiation, and growth and metastasis in mice." (PMID 26268733, 2015). "The enzyme is directed to nucleoli of cancer cells by insulin/IGF-1–PI3K signaling pathway, and appears to interact with the ribosomal proteins." (PMID 26033454, 2015). "Together with insulin and ERbB signaling and cancer, they were the top four signaling pathways with the lowest p-values." (PMID 26536660, 2015). "Researchers later determined that insulin has a similar effect on the growth of other forms of cancer." (PMID 26029167, 2015). "While some family members such as cathepsins B, C and S, are supplied to the PNET tumor site by CD45+ inflammatory cells, cathepsin L is predominantly expressed by insulin-producing cancer cells." (PMID 25927437, 2015). "An increased insulin or IGF-1 level, which presents in T2DM, obesity, and acromegaly, is strongly associated with increased cancer risk and mortality." (PMID 25866823, 2015). "Many imprinted genes are often epigenetically affected in human cancers due to their functional linkage to insulin and insulin-like growth factor signaling pathways." (PMID 26338779, 2015). "In addition to the possible direct oncogenic effects of insulin on the proliferative and anti-apoptotic signaling in cancer cells, insulin is also implicated in various aspects of the maintenance of whole-body homeostasis, including the action of sex hormones, which may contribute to carcinogenesis." (PMID 26720346, 2015). "Several cancer prevention and treatment interventions targeting insulin/IGF signaling or downstream factors will also be described, as well as recent results from trials testing these agents." (PMID 26029167, 2015). "Although the anti-cancer effects of the KD are largely attributed to a reduction in the glycolytic substrates and insulin signaling which fuel cancer metabolism, emerging evidence suggests that ketones have a therapeutic potential of their own." (PMID 26061868, 2015). "In cell cultures, IGF/insulin promotes proliferation, survival, and migration of various cancer cells." (PMID 26074875, 2015). "In cancer researches, some experimental studies involving insulin associated signaling pathways pointed out the possible synergism between insulin and P-glycoprotein in cancer chemoresistance." (PMID 26084465, 2015). "Aside from AMPK, adiponectin is a potent inhibitor of PI3K/AKT /mTOR that is able to reduce cancer cell growth exerted by insulin and growth factor-induced signaling." (PMID 26320190, 2015). "Most epidemiological studies have suggested that cancer in diabetic women can be modulated by insulin sensitizers such as metformin and TZDs." (PMID 25866823, 2015). "From all apparent evidences, we propose that the insulin/IGF system is still an effective target for cancer therapy." (PMID 25699021, 2015). "The genes containing cancer-specific AS events are significantly enriched for functions in cell cycle, cell adhesion/migration, and insulin signaling pathway." (PMID 25749525, 2015).